EGLN3 (egl-9 family hypoxia inducible factor 3)
Diseases named in the same sentence as EGLN3 in open-access papers (continued):
Sharing a sentence is not in itself a finding about the gene and the disease.
lung adenocarcinoma (5 papers, 2019 to 2025). A carcinoma that arises from the lung and is characterized by the presence of malignant glandular epithelial cells. "EGLN1 overexpres-sion was associated with worse survival in cervical squamous cell carcinoma (CESC), pancreatic adenocarcinoma (PAAD), and neuroblastoma (NB), while EGLN3 was linked to poor survival in CESC, lung adenocarcinoma (LUAD), and kidney cancers." (PMID 40464184, 2025). "The bioinformatics analysis demonstrated that EGLN3 expression was higher in lung adenocarcinoma (LUAD) compared to adjacent normal tissues and its high level was positively associated with tumor purity, histological type, higher stage, as well as poor prognosis." (PMID 38928200, 2024). "Consequently, we concluded that lncRNA GSEC acts as an oncogene in lung adenocarcinoma by targeting miR-873-3p to modulate EGLN3, which might be the mechanism of LUAD progression." (PMID 37842058, 2023).
neuroblastoma (5 papers, 2012 to 2025). Neuroblastoma (NB) is the most common solid, extracranial childhood tumor. "Indeed, mutations of several genes implicated along the EglN3-dependent pathway have been found to associate with neuroblastoma and malignancies of neural crest origin such as paraganglioma and pheochromocytoma." (PMID 27097110, 2016). "One of the mechanisms that give rise to neuroblastoma is the failure of neural progenitors to undergo apoptosis via an EglN3-dependent pathway when nerve growth factor (NGF) becomes limiting during development." (PMID 27097110, 2016).
Obesity (5 papers, 2010 to 2024). Accumulation of substantial excess body fat. "Abcg1, Aldoa, Mrap, Pex13, Aldh6a1, Egln3, G0s2 and Syn2 are significantly increased in adipose or liver tissue of ob/ob mice compared with lean mice, suggesting these genes are associated with obesity, are very rarely reported to be related to adipogenesis." (PMID 34974794, 2022).
cholangiocarcinoma (4 papers, 2021 to 2025). A carcinoma that arises from the intrahepatic biliary tree (intrahepatic cholangiocarcinoma) or from the junction, or adjacent to the junction, of the right and left hepatic ducts (hilar cholangiocarcinoma). "A novel pathway through which USP9X / EGLN3 provides promising diagnostic and therapeutic targets against cholangiocarcinoma." (PMID 34112167, 2021). "EGLN3 is associated with various tumor conditions, and USP9X relieves cholangiocarcinoma by upregulating EGLN3." (PMID 37842058, 2023). "Immunoblotting and immunohistochemistry were used to assess the expression profiling of USP9X and EGLN3 in cholangiocarcinoma patients." (PMID 34112167, 2021). "USP9X positively regulated the expression level of apoptosis pathway genes de through EGLN3 thus involved in apoptosis of cholangiocarcinoma." (PMID 34112167, 2021). "In this study, USP9X modulates the malignant potential of cholangiocarcinoma through regulation of EGLN3." (PMID 34112167, 2021). "In summary, this study is the first to demonstrate that USP9X exerts tumor-suppressive effects in cholangiocarcinoma by deubiquitinating and stabilizing the EGLN3 protein, thereby activating the KIF1Bβ-mediated apoptotic pathway and establishing a novel USP9X-EGLN3-KIF1Bβ tumor-suppressive axis." (PMID 41301681, 2025). "Therefore, USP9X exerts its tumor inhibitory effect through EGLN3 thus regulated apoptosis pathway by KIF1Bβ in cholangiocarcinoma." (PMID 34112167, 2021). "On the basis of these analyses, we next examined whether EGLN3 expression correlates with USP9X in cholangiocarcinoma cells." (PMID 34112167, 2021). "In cholangiocarcinoma (CCA), the tumor suppressor KIF1Bβ induced apoptosis and was up-regulated by Egl nine homolog 3 (EGLN3), and ubiquitin-specific peptidase 9X (USP9X) acted to de-ubiquitinate and stabilize EGLN3 thereby accelerating this process." (PMID 38433242, 2024). "But, the function of EGLN3 for cholangiocarcinoma remains unknown." (PMID 34112167, 2021). "Therefore, we examined the function of EGLN3 in cholangiocarcinoma." (PMID 34112167, 2021). "Notably, in cholangiocarcinoma, USP9X promotes apoptosis by deubiquitinating EGLN3 and regulating the expression of KIF1Bβ, highlighting its crucial role in tumor suppression." (PMID 41301681, 2025). "To further identify the clinical relevance of our findings, we evaluated the correlation of expression levels between USP9X and EGLN3 in 5 pairs of primary cholangiocarcinoma and matched adjacent noncancerous tissues by immunoblotting." (PMID 34112167, 2021). "Moreover, the level of EGLN3 in cholangiocarcinoma tissues was lower than adjacent noncancerous tissues." (PMID 34112167, 2021).
hepatocellular carcinoma (4 papers, 2012 to 2024). A malignant tumor that arises from hepatocytes. "Similarly, in hepatocellular carcinoma (HCC), the EGLN3 mRNA and protein levels were significantly higher in tumor tissues compared to adjacent non-tumor liver samples." (PMID 38928200, 2024).
cervical cancer (2 papers, 2017 to 2022). A primary or metastatic malignant neoplasm involving the cervix. "In particular, the NDRG1, HK2, PLOD2, EGLN3, and NPC1 genes showed a higher expression in tumors than in normal tissues, and cervical cancer patients overexpressing these genes had a poor prognosis compared with those who showed low expression levels of these genes." (PMID 36551576, 2022).
COVID-19 (2 papers, 2022 to 2025). A disease caused by infection with severe acute respiratory syndrome coronavirus 2. "Similarly, activation of COX2 and HIF-1α in COVID-19 has been shown to upregulate the antiapoptotic antiproliferative microenvironment (BCL2, BNIP3) and M1 immune system {nuclear factor kappa B (NFKB), Egl-9 family hypoxia inducible factor 3 (EGLN3), CXCL8, TNF-α, and IL-6 }." (PMID 36671699, 2022).
disc degeneration (2 papers, 2024). "The findings indicated that HIF-2α, CAIX, PPP1R15A, VEGFA, and EGLN3 could potentially serve as new indicators of disc degeneration." (PMID 38254196, 2024). "Measuring the target index, HIF-2α, CAIX, PPP1R15A, VEGFA, and EGLN3 could potentially serve as new indicators for disc degeneration." (PMID 38254196, 2024). "Whereas increased, Egln3, or PHD3, could implicate impaired oxygen sensing mechanisms, as this protein serves as co-activator of HIF-1 and loss-of-function of Egln3 in mice has been shown to promote disc degeneration." (PMID 38510179, 2024).
heart failure (2 papers, 2016 to 2023). Inability of the heart to pump blood at an adequate rate to meet tissue metabolic requirements. "miR-20a, as a member of the miR-17-92 cluster, was reported to have been dysregulated in heart failure patients treated with cardiac resynchronization therapy and inhibit stress-induced cardiomyocyte apoptosis by targeting Egln3/PHD3." (PMID 27543062, 2016).
kidney cancer (2 papers, 2021 to 2025). Primary or metastatic malignant neoplasm involving the kidney. "In addition, EGLN3 methylation is significantly different in kidney cancer tissue versus normal tissue (Figure A3,) suggesting that epigenetics might play a role in PHD3 expression in ccRCC." (PMID 33799686, 2021).
diabetic cardiomyopathy (1 paper, 2024). Diabetic cardiomyopathy is a disorder of the heart muscle in people with diabetes. "We constructed a diagnostic model of DCM, and OXCT1, CACNA2D2, BCL7B, EGLN3, GABARAP, and ACADSB were potential biomarkers, which may provide new insights for improving the ability of early diagnosis and treatment of diabetic cardiomyopathy." (PMID 38469146, 2024). "We found diagnostic and predictive biomarkers of type 2 DCM consisting of OXCT1, CACNA2D2, BCL7B, EGLN3, GABARAP, and ACADSB, which may reduce the difficulty of early prediction of diabetic cardiomyopathy, and lay a foundation for prospective research." (PMID 38469146, 2024).
iron deficiency (1 paper, 2022). "mRNA regulation of Ankyrin repeat domain 37 (ANKRD37), prolyl 4-hydroxylase (P4ha1), and HIF prolyl hydroxylase 3 (EGLN3) are the most well-known marker genes for the hypoxic signal under iron deficiency." (PMID 36494833, 2022). "In the current study, we selected marker genes that were regulated by iron deficiency including iron transporters (DMT1, TFR, and FPN) and iron-dependent hypoxic genes (ANKRD37 and EGLN3)." (PMID 36494833, 2022).
kidney tumor (1 paper, 2013). "The VHL-/- 786-O cells depleted of EGLN3 grew tumors just as well as the control cells, suggesting that EGLN3 inhibition alone is not a good way to suppress kidney tumor growth." (PMID 24260413, 2013).
oral cancer (1 paper, 2024). "Notably, HIF1A and EGLN3 mRNA levels show an upregulation in metastatic HNSCC cell lines when compared to cell lines originating from oral cancer." (PMID 38928200, 2024).
oral cavity tumor (1 paper, 2024). "The EGLN3 mRNA levels were significantly different in tumor tissues in both age groups, in male patients, in different tumor stages and grades, and, in the oral cavity tumor location." (PMID 38928200, 2024). "The oral cavity tumor results reflected data without stratification, namely, we observed a significant decrease in EGLN1 levels compared to normal tissues (p = 0.0032), while EGLN3 and HIF1A mRNA levels were higher (p < 0.0001; p = 0.0012)." (PMID 38928200, 2024).
pancreatic endocrine carcinoma (1 paper, 2024). An aggressive, high-grade and poorly differentiated carcinoma with neuroendocrine differentiation that arises from the pancreas. "Moreover, high expression of nuclear forms of EGLN2 and EGLN3 was associated with worse survival in pancreatic endocrine cancer." (PMID 38928200, 2024).
polycythemia (1 paper, 2019). Abnormally high mass or concentration of red blood cells in the blood, either due to an increase in erythropoiesis or a decrease in plasma volume. "Although association analysis with microsatellite markers in an Andean high-altitude population shows a possible association between EGLN3 (marker D14S1049) and severe polycythemia, no susceptible association between SNPs in EGLN3 and HAPC is reported." (PMID 31827636, 2019).
tumor (92 papers, 2007 to 2025). "PHD3, which is a protein encoded by the EGLN3 gene, has tumor suppressor functions in various cancer types." (PMID 35174098, 2022). "Taken together, deficiency of EGLN3 activity in the stromal cells (particularly macrophages in the current study) restrains cancer growth by mounting a robust anti-tumor immune response and restricting angiogenesis." (PMID 35124697, 2022). "We propose that Egln3 encodes an additional, molecular participant that governs tumor vascular normalization." (PMID 22905089, 2012). "To address whether the tumor suppressive phenotype of Egln3 was intrinsically linked to hydroxylase activity, we generated an enzymatically defective Egln3 mutant through the alteration of a catalytically critical histidine residue (i.e. H196A)." (PMID 22905089, 2012). "In this study, the authors uncovered that USP9X enhances EGLN3 protein stability via deubiquitination, thereby reinforcing its tumor-suppressive effects." (PMID 41301681, 2025). "Research indicates that EGLN3 inhibits tumor growth by suppressing EGFR signaling, inducing G1-phase cell cycle arrest, and promoting apoptosis." (PMID 41301681, 2025). "EGLN3, a member of the EGLN family, functions as a prolyl hydroxylase and has been implicated as a tumor suppressor in multiple cancers." (PMID 41301681, 2025). "This process promotes cancer cell apoptosis and inhibits tumor progression, positioning the USP9X/EGLN3 axis as a promising diagnostic and therapeutic target for CCA." (PMID 41301681, 2025). "Our analysis revealed a significant increase in overall survival (OS) among patients with high EGLN2 mRNA levels in tumor tissues (p = 0.0052), alongside those with low levels of EGLN3 (p = 0.0272)." (PMID 38928200, 2024). "Reduction of EGLN3 expression in tumor cells suppresses EGFR internalization, resulting in its hyperactivation." (PMID 38928200, 2024). "The study results showed that the reduction in expression levels of all four investigated genes, CA9, NDUFA4L2, EGLN3, and BHLHE41, is associated with tumor metastasis." (PMID 37443682, 2023). "A decreased level of EGLN3 expression leads to a disruption of the hydroxylation of extracellular signal-regulated kinase 3 (Erk3)—one of the key players in regulating tumor progression." (PMID 37443682, 2023). "Studies have shown that EGLN3 is involved in the metabolism and angiogenesis of oxygen from tumor cells, which in turn affects tumor cell proliferation." (PMID 36277897, 2022). "EGLN3 exhibits a variety of biological functions, ranging from regulating cell signaling, cellular metabolism, cell cycle, apoptosis, and migration of cancer cells; and EGLN3 plays key roles in tumor growth and progression." (PMID 35124697, 2022). "This work demonstrates that inactivation of EGLN3 in malignant and stromal cells suppresses tumor by orchestrating reciprocal interplays between cancer cells and the TME." (PMID 35124697, 2022). "Adoptive transfer of macrophages with inactivated EGLN3 restrains tumor growth by mounting anti-tumor immunity and restricting angiogenesis." (PMID 35124697, 2022). "We demonstrate that inactivation of EGLN3 in malignant and stromal cells suppresses tumor by orchestrating the reciprocal interplays between cancer cells and the TME." (PMID 35124697, 2022). "TFAM is hydroxylated by EGLN3 and subsequently bound by the von Hippel–Lindau tumour-suppressor protein, which stabilizes TFAM by preventing mitochondrial proteolysis." (PMID 35760869, 2022). "LLC cells harboring inactivated EGLN3 exhibit reduced tumor burden via mitigating immunosuppressive milieu and inducing cancer senescence." (PMID 35124697, 2022). "Under hypoxic conditions, increased expression of EGLN3 is necessary for survival and G1 to S transition of tumor cells, suggesting that in VHL-single hit cells a condition of modified steady state and feedback regulation exists that favors RCC development." (PMID 27682873, 2017).
tumor (continued). "Strikingly, induction of Egln3 normalized tumor capillary morphology, reducing the percentage of disorganized and distended vascular branches (0% tumor capillaries >25μm in diameter)." (PMID 22905089, 2012). "Egln3 up-regulation evoked a relatively normalized tumor capillary structure with 80% of capillaries having diameters of <26μm, 20% with diameters of 26–50μm and 0% of >50μm." (PMID 22905089, 2012). "We noted that Egln3 reduced tumor Vegf production and induced the normalization of capillary structure." (PMID 22905089, 2012). "Through intracranial tumorigenesis and in vitro assays, we demonstrate for the first time that Egln3 was sufficient to decrease the kinetics of tumor progression and increase survival." (PMID 22905089, 2012). "Consistent with our intracranial engraftment assays, Egln3 expression dramatically reduced tumor size." (PMID 22905089, 2012). "Within the top 20 genes ranked by Notch pathway-guided COCA, there are several genes related to differentiation (Tdgf1, Egr1 and Lefty1), cell growth (Ddit4, Hk2, Phlda2, Egln3 and Igfbp1) and tumor/cancer development (Afp, Sfrp2, Egr1, Hk2 and Phlda2)." (PMID 20353603, 2010). "EGLN3, a key gene that adapts to the hypoxic microenvironment, has various biological functions such as regulation of cell signaling, metabolism, cell cycle, and migration of cancer cells, and plays a vital role in tumor growth and progression." (PMID 37400770, 2023). "Interestingly, EGLN3 was another significant, independent prognostic gene for OS in the TCGA-LIHC dataset among the other metabolism-associated genes related to tumor FDG uptake." (PMID 35174098, 2022). "Studies using EGLN3 catalytically inactive knock-in mice indicate that inactivation of EGLN3 hydroxylase in host cells ameliorates LLC cancer growth through reprogramming the tumor microenvironment (TME)." (PMID 35124697, 2022). "Adoptive transfer of macrophages with inactive EGLN3 activity curbed tumor angiogenesis." (PMID 35124697, 2022). "We then determined the impact of EGLN3 inactivation on tumor angiogenesis." (PMID 35124697, 2022). "We tested the surmise that EGLN3 inactivation in host cells is protective against tumor growth." (PMID 35124697, 2022). "On the other hand, Egln3 (PHD3) not only functions as a tumor suppressor but may also promote fibrosis and anti-inflammatory responses and prevent neutrophil apoptosis under hypoxic conditions." (PMID 35625760, 2022). "Consequently, the expression of CA9, NDUFA4L2, EGLN3, BHLHE41, VWF, IGFBP3, and ANGPTL4 is associated with ccRCC tumor progression and decreases at stage 4 after initial growth relative to normal tissues." (PMID 34046336, 2021). "USP9X elicited tumor suppressor role by preventing degradation of EGLN3." (PMID 34112167, 2021). "Prolyl hydroxylase 3 (EGLN3) is widely accepted as a tumor suppressor." (PMID 34112167, 2021). "Therefore, inactivated EGLN3 in LLC cells exhibited a tumor-inhibitory effect." (PMID 35124697, 2022). "At the initial stage of tumor development, the activation of the genes under consideration provides adaptation to hypoxia, accompanied by a metabolic shift, i.e., the development of glycolysis and a decrease in oxidative phosphorylation (EGLN3, NDUFA4L2, ANGPTL4, CA9, and, apparently, IGFBP3)." (PMID 34046336, 2021). "Therefore, USP9X exerts its tumor inhibitory effect through EGLN3." (PMID 34112167, 2021). "It is also known that EGLN3 has other hydroxylase targets and have HIF-dependent and HIF-independent biological activities, so we wondered whether EGLN3 loss would have any impact on tumor growth." (PMID 24260413, 2013). "In addition, quantification of total tumor Vegf, Klf5 and Oct4 transcript levels indicated that Egln3H196A induction did not inhibit Hif-mediated transcription whereas tumors expressing wild-type Egln3 displayed decreases in Vegf, Klf5 and Oct4 in vivo." (PMID 22905089, 2012).